SFRP1 (secreted frizzled related protein 1)
Diseases named in the same sentence as SFRP1 in open-access papers (continued):
Sharing a sentence is not in itself a finding about the gene and the disease.
cancer (continued). "This component features COL10A1, ITIH5, ADIPOQ, ADAMTS5, GPC3, SFRP1, and RARRES2 genes, pointing to their involvement in cancer-related cellular structures." (PMID 38253993, 2024). "A contrasting pattern of similarity emerges among carcinomas originating from uterine, pulmonary, and hepatic tissues, where genes like CTHRC1, ADH1B, GHR, DES, SFRP1, and RNF150 share similar weights." (PMID 39596491, 2024). "Actually, many studies have indicated that SFRP1 has anti‐oncogene activity and that SRFP1 extensively participates in dysregulation of cancer cell migration, proliferation, and invasion." (PMID 36259450, 2023). "While our study unraveled the inhibit function of SFRP1 in oral squamous cancer cells, it is necessary to expose a deeper mechanistic understanding of SFRP1-dependent signaling pathways, which could contribute to a cancer-specific single agent or combination therapy for OSCC." (PMID 35892344, 2022). "Of which, the top 20 differential expressed genes (DEGs) were mainly related to the progression of malignant tumors, including SYT12, CLDN10, COL9A3, SFRP1, MT1G, MTIH, etc.." (PMID 36253446, 2022). "SFRP1, SFRP2, and SFRP5 were significantly correlated with the clinical cancer stage in GC patients." (PMID 34205081, 2021). "Cells in cluster 5 resembled those in cluster 7 of DNs, and included cells with aberrant neuronal identity that expressed neuronal genes (GAP43, NEFM, DCX, HES6) and cancer-related proliferative genes (CRABP1, MYC, SFRP1)." (PMID 33771987, 2021). "Simultaneous methylation of HIC1 + SFRP1 and DAPK1 + SOX1 exhibited sensitivity of 78.82 and 72.94%, respectively with specificity of 77.14% (AUC = 0.87 for both gene panels) for cancer detection." (PMID 34778370, 2021). "This allowed the selection of the key EMT-correlated genes that uncover functional implications in cancer; this is the case of direct correlation of NOX4 with DACT3 and SFRP1 and inverse correlation of NOX4 and BMP5." (PMID 34073426, 2021). "SFRP1 suppresses WNT signalling; concomitantly, hedgehog signalling promotes stemness of cancer cells." (PMID 32764696, 2020). "The epigenetic regulation of SFRP1 expression will also be underscored with additional emphasis on the potentials of SFRP1 in modulating responses toward chemotherapeutic and epigenetic-modifying drugs, which may encourage the development of novel drugs for cancer treatment." (PMID 32074995, 2020). "Our results showed six genes (p16, RASSF1A, GSTP1, APC, p15 and SFRP1) in HBV-positive carcinoma tissues, one gene (GSTP1) in HBV-positive adjacent tissues and two gene (p16 and APC) in HBV-positive carcinoma serums, which were significantly hypermethylated." (PMID 31772678, 2019). "Expression of SFRP1 leads to antitumor synergy of combined HDAC and methyltransferase inhibitors in chemo-resistant cancers." (PMID 29371858, 2018). "We identified SFRP1 and snoRNAs (especially SNORD115 and SNORD114) as the initial regulators of cancer progression, accompanied by significant changes in extracellular matrix organization." (PMID 30647841, 2018). "We examined DNA methylation levels of SFRP1, SFRP2, SFRP5, DKK2, DKK3, mir34b/c, RASSF1A, IGFBP7, CDKN2A, and MLH1 in cancerous glands and normal crypts isolated from cancer tissue and the surrounding normal mucosa." (PMID 28533824, 2017). "Compared to surrounding normal colonic crypts, the methylation levels of SFRP1, SFRP2, SFRP5, DKK2, DKK3, mir34b/c, and RASSF1A in MSS CRCs were significantly higher in cancer crypts." (PMID 28533824, 2017). "As a control, such treatment reactivated expression of SFRP1 and SFRP2 genes known to be silenced by methylation in various types of cancers." (PMID 27626696, 2016). "Despite the apparent similar roles of SFRP1 and SFRP2 proteins, the significance of SFRP2 silencing in human cancers is generally less clear." (PMID 26337424, 2016).
cancer (continued). "This study suggests a new regulatory mechanism of SFRP1, AXIN2, and ICAT, and also implies that the three genes play a significant role in mediating cancer stemness." (PMID 26337084, 2015). "In our investigation, mutation carriers over 50 years old with a previous CRC diagnosis showed a significantly elevated average degree of methylation of SFRP1 and SLC5A8 vs. cancer-free individuals of a comparable age." (PMID 26203307, 2015). "While the sensitivity and specificity of cancer detection using ZNF671 methylation alone was 57.7% and 89.5%, combining hypermethylation of ZNF671 with that of IRF8 and SFRP1 increased the sensitivity to 96.2%." (PMID 26320192, 2015). "We therefore examined the sensitivity and specificity of cancer detection in urine by combining methylated ZNF671 with methylation of two other TSGs (IRF8 and sFRP1) using a previously published urine sample cohort (26 UCs and 19 non-cancerous controls)." (PMID 26320192, 2015). "The prospective LS series indicated significantly higher frequencies of hypermethylation for SFRP1 (95 %, p = 0.006) and SFRP2 (67 %, p = 0.012) in carcinomas vs. normal colonic mucosa." (PMID 26203307, 2015). "p16, TFPI2, the cadherins E-cadherin and CDH13, and the secreted frizzle-related proteins (SFRPs) SFRP1 and SFRP5 were desilenced in cancer cell lines." (PMID 23593653, 2013). "These 58 predicted target mRNAs included many genes previously reported to be involved in tumorigenesis of CRC or other malignant tumors such as KLF4, SFRP1, SFRP2, RNF138." (PMID 22703586, 2012). "For methylation detection in voided urine samples of cancer patients, the sensitivity and specificity of using any of the methylated genes (IRF8, p14 or sFRP1) by qMSP was 86.7% and 94.7%." (PMID 21599969, 2011). "Two members of the secreted frizzled-related protein (SFRP) family, SFRP1 and SFRP4, were more frequently down-regulated in MSI-positive carcinomas compared with MSI-negative carcinomas." (PMID 20368795, 2010). "Because sFRP1 is a Wnt antagonist and the Wnt/β-catenin/TCF axis is aberrantly activated in cancer, it is plausible that downregulation of sFRP1 contributes to abnormal activation of the β-catenin/TCF complex." (PMID 19277043, 2009). "The immunohistochemical staining revealed abundant expression of SFRP1 in the cell membrane and cytoplasm of paracancerous tissues, whereas it was not present in cancer tissue." (PMID 37859826, 2023). "This screen led to the identification of 430 compounds as primary hits based on a pre-defined cut-off for the differential cell growth between the SFRP1 negative and positive cancer cells." (PMID 36139547, 2022). "SFRP1 repression might potentiate the oncogenic function of the WNT signaling pathway, particularly in β-catenin mutant cancers." (PMID 32189106, 2020). "The downregulation of SFRP1 expression in cancer can be regulated through different mechanisms such as non-coding RNA (ncRNA), DNA methylation, allelic imbalance, or genomic alterations." (PMID 32074995, 2020). "However, SFRP1′s modulation of ADAM10 and Wnt signaling has a flip side, which includes the promotion of cancer and the negation of other beneficial aspects." (PMID 32098349, 2020). "We show that while SFRP1 is frequently silenced in many cancers through methylation, the other SFRPs do not undergo this silencing event." (PMID 28218291, 2017). "We examined the DNA methylation levels of SFRP1, SFRP2, SFRP5, DKK2, DKK3, mir34b/c, RASSF1A, IGFBP7, CDKN2A, and MLH1 in normal colonic crypts isolated from regions that were adjacent to the cancer, as well as distal and proximal regions (left and right sides)." (PMID 28533824, 2017). "Considering down-regulated genes in LSC GFP+ cells, expression level of several of them inversely correlates with cancer aggressiveness, notably in prostate such as SPARCL1, a negative regulator of bud expansion and prostasphere growth, and SFRP1, a negative regulator of Wnt pathway." (PMID 27081082, 2016).
cancer (continued). "Similarly, the methylation of SFRP1/2/4/5 was also present in normal control samples, although SFRP2 showed the highest cancer specificity among the SFRP genes." (PMID 25487617, 2015). "The dysregulation of SFRP1, AXIN2, and ICAT has been largely reported in numerous types of cancers." (PMID 26337084, 2015). "Moreover, SFRP1 and SFRP2 expressions were significantly lower in the untreated cancer cell lines compared to the corresponding normal controls (data not shown)." (PMID 26203307, 2015). "According to our rating criteria, 52 (66.7%) of the 78 carcinoma specimens were categorized as negative for SFRP1 expression and 26 (33.3%) were categorized as positive." (PMID 24594839, 2014). "Previous studies have shown that promoters of most WNT antagonistic genes (sFRP1, sFRP2, sFRP3, sFRP5, DKKs, and WIF1) are methylated or epigenetically silenced in RCC, which results in uninhibited WNT signaling during cancer initiation or progression." (PMID 23094073, 2012). "Exploration on the molecular mechanisms suggests that activation of the lncMEG3/miR‐542‐3p/SFRP1 axis contributed to the antitumor action of MTE, which gives insight into the crucial significance of lncRNA/miRNA/mRNA and pathways in the TCM treatment of patients with cancers." (PMID 36756719, 2023). "PIK3CA-mutant cancers displayed higher expression of 12 of the 17 Wnt genes compared to PIK3CA wild-type tumors, including five Wnt target genes (LEF1, MYCN, FZD7, SFRP2, and TNFRSF11B) and seven Wnt signaling components (TCF7L1, TCF7L2, CTNNB1, FZD4, SFRP1, WNT5A, and MSX2)." (PMID 34035258, 2021). "In six genes (p16, RASSF1A, GSTP1, APC, p15 and SFRP1), there was significant difference in the level of hypermethylation between HBV-positive carcinoma tissues and HBV-negative carcinoma tissues, revealing that HBV infection could induce methylation of these genes in HCC." (PMID 31772678, 2019). "Furthermore, differentially hydroxymethylated genes within this pathway, including the PCa-inhibitory genes secreted fizzled-related protein 1 (SFRP1) and Dab, mitogen-responsive phosphoprotein homolog 2 (DAB2), exhibited significantly lower expression in cancer than in the normal cell line." (PMID 26981160, 2016). "We demonstrate that when SFRP1 is downregulated in a non-malignant immortalized mammary epithelial cell line, sensitivity to Wnt signaling is enhanced and the cells exhibit distinct hallmarks of cancer progression." (PMID 19422694, 2009). "Hypermethylation of SFRP1 was found in other cancers, but had not been studied before in PCa." (PMID 15292941, 2004). "Furthermore, the extent of methylation was significantly greater in EAC compared to BE for six genes (CDKN2A, ID4, RBP1, RUNX3, SFRP1, and TMEFF2), suggesting that methylation of these genes occurs early in the progression of BE, with increased methylation as the disease advances toward cancer." (PMID 40149421, 2025). "Importantly, further statistical analysis revealed that in dependency of the cancer subtype model SFRP1 may affect the canonical and non-canonical Wnt pathway (p<0.01), respectively." (PMID 25036590, 2014). "Therefore, transfected MCF7 cancer cell lines with and without the C2TSG protein SFRP1 represent a suitable model for a differential HTS with the CellTiter-Glo® assay as a read-out." (PMID 36139547, 2022). "Indeed, as proof of the validity of our method, we identified many genes that are known to be differentially methylated across various cancer types (CDKN2A, CDKN2B, MGMT, SFRP1), in addition to many novel genes not previously known to be regulated by DNA methylation." (PMID 25486910, 2014).
adenocarcinoma (9 papers, 2008 to 2025). A common cancer characterized by the presence of malignant glandular cells. "The expression of SFRP1 was increased in normal and in adenocarcinoma cells." (PMID 32764696, 2020). "Five remaining loci, CDH13, CDX2, OPCML, SFRP1 and TWIST1 were designated as “late” loci; significantly elevated DNA hypermethylation was only detected in adenocarcinoma, as compared with AIS." (PMID 21731750, 2011). "SFRP1 hypermethylation tended to occur frequently to tumors of patients with ≥60 years old, no lymph nodes involved, adenocarcinoma and moderate or well differentiation degree in the current study." (PMID 31830937, 2019). "When we sub-grouped patients based on their demographic characteristics, we found that SFRP1 methylation significantly reduced DCR in patients older than 65 (P = 0.038) and sFRP5 methylation significantly reduced DCR in patients suffered adenocarcinoma (P = 0.042)." (PMID 23009178, 2012).
infection (7 papers, 2015 to 2024). The state of being infected such as from the introduction of a foreign agent such as serum, vaccine, antigenic substance or organism. "The downregulation of SFRP1 in infected animals indicates that blood cells during early stages of infection preferentially activate humoral immunity to resist the parasite invasion." (PMID 35320269, 2022). "AAV-Sfrp1 was injected to generate the overexpression of Sfrp1; the infection efficiency of AAV-Sfrp1 was examined 5 weeks after the first injection by immunoblotting." (PMID 33468190, 2021). "In contrast, Sfrp1 mRNA in HSCs was significantly decreased since post infection, which was reversely related to the sja-miR-1 level in HSCs." (PMID 32232014, 2020). "We then analyzed the expression of sja-miR-1 and Sfrp1 in HSCs isolated from the liver samples of infected mice at various time points post infection." (PMID 32232014, 2020). "At every 24 hours within 4 days after lentiviruses infection of SiHa and CaSki, we used Q-PCR to analyze the expression of E6, E7, DNA methyltransferase genes (DNMT1, DNMT3A, DNMT3B and DNMT3L), and tumor suppressor genes (MT1G, NMES1, RRAD, SFRP1, SPARC and TFPI2)." (PMID 26329329, 2015).
cardiovascular disease (4 papers, 2016 to 2023). "sFRP-1 overexpression is associated with an increased risk of cardiovascular diseases, coronary artery disease (CAD), diabetes and even obesity." (PMID 37484982, 2023). "sFRPs have been shown to alleviate collagen deposition and fibrosis in cardiac tissue; however, systemic sFRP1 is significantly higher in patients with cardiovascular disease, and its increased circulating levels are associated with the development of cardiovascular diseases." (PMID 34383712, 2021). "Higher levels of sFRP-1 precede cardiovascular events and may prove a useful biomarker in cardiovascular diseases." (PMID 37484982, 2023).
colorectal (3 papers, 2006 to 2023). "Because hyperactive Wnt signaling is associated with colorectal carcinogenesis, our observation that RS and polydextrose suppressed SFRP1 expression is counterintuitive because higher consumption of NDCs is associated with lower CRC risk." (PMID 28077379, 2017).
neurodegenerative disease (3 papers, 2016 to 2023). A disorder of the central nervous system characterized by gradual and progressive loss of neural tissue and neurologic function. "Moreover, HUGO: SFRP1 and WNT3 genes probably play a role in the canonical Wnt/β-catenin signaling pathway, an essential constituent in the progress of neurodegenerative diseases." (PMID 37427327, 2023). "In conclusion, our work identifies SFRP1 as a potential signal that maintains progenitors of the aged human SVZ in a quiescent state, supporting the possibility to re-activate progenitors of the aged human brain to regenerate the brain following injury or neurodegenerative diseases." (PMID 35210419, 2022).
head and neck tumor (1 paper, 2013). "This analysis revealed that hypermethylation of CCNA1, DAPK, MGMT, SFRP1 and TIMP3 was frequent in head and neck tumor (40-70%)." (PMID 24359512, 2013).
immune disease (1 paper, 2025). "The analysis revealed the significant enrichment of genes such as HLA-DQB1, HLA-DPA1, S100A8, SFRP1, CD247, CTSH, and LAMP3, which are linked to inflammatory and immune disease pathways." (PMID 40426861, 2025).
SFRP1 also shares sentences with these, for which no sentence is quoted: head and neck squamous cell carcinoma (4 papers); acute myocardial infarction (3); pancreatic ductal adenocarcinoma (3); Barrett esophagus (2); brain cancer (2); Hypertension (2); lung squamous cell carcinoma (2); neurological diseases (2); Osteopenia (2); ovarian tumors (2); reproductive system disease (2); adenomyosis (1); adrenocortical tumors (1); anaplastic astrocytoma (1); angle-closure glaucoma (1); asthma (1); atopic dermatitis (1); autism (1); benign ovarian tumors (1); bladder (1); brain glioma (1); breast hyperplasia (1); calcification (1); carcinoma in situ (1); cardiac diseases (1); cardiac hypertrophy (1); cervical adenocarcinoma (1); chordoma (1); CNS tumor (1); colon adenocarcinoma (1).
A further 41 diseases each share a sentence with SFRP1 in 1 paper.